HIF1A (hypoxia inducible factor 1 subunit alpha)
Diseases named in the same sentence as HIF1A in open-access papers (continued):
Sharing a sentence is not in itself a finding about the gene and the disease.
tumor (continued). "HIF-1α knockdown directly repressed tumor growth, whereas IL-8 knockdown indirectly repressed tumor growth." (PMID 28053598, 2017). "HIF1-α has been demonstrated to be an key predictor of tumor progression for several types of solid cancers." (PMID 28878214, 2017). "The mechanisms of cancer-induced HIF-1α are multifactorial, including a decrease in HIF-1α degradation that is associated with intra-tumor hypoxia and an increase in HIF-1α production that is associated with oncogene expression." (PMID 29152137, 2017). "HIF-1α also reduces expression of tumour suppressor SIRT3 which functions in activating antioxidants in mitochondria of healthy cell." (PMID 28373964, 2017). "Stable suppression of AGT expression in CNE2 tumor cells by RNA interference (RNAi) greatly attenuated HIF-1α accumulation in the pimonidazole-positive hypoxic regions of the xenografted tumors formed in nude mice." (PMID 28205588, 2017). "The protein VHL is a tumor suppressor that forms E3 ubiquitin ligase complex, which negatively regulates HIF-1α by promoting its polyubiquitination." (PMID 29068413, 2017). "Sirtuins (SIRTs) are nicotinamide adenine dinucleotide (NAD+)-dependent deacetylases and mitochondrial SIRT3 is known to be a tumor suppressor via its ability to suppress ROS and hypoxia inducible factor 1α (HIF-1α)." (PMID 29108235, 2017). "In this context it is worth noting that AMPK has been shown to negatively regulate aerobic glycolysis in cancer cells by inhibiting HIF-1α stabilization, pointing to a role for this kinase as a tumor suppressor." (PMID 29190880, 2017). "Then we implanted 3 × 104 GL261-luc HIF1α-ShRNA cells into C57 mice brain and observed that the tumor size was much smaller than control groups with the same tumor cells seeded." (PMID 28427209, 2017). "In a hypoxic environment, this angiogenic process promotes tumor development through HIF-1α-induced upregulation of miR-494." (PMID 29113423, 2017). "The percentage of HIF‐1α+ viable tumour cells was significantly reduced in the tumours from mice treated with AZD5363, relative to vehicle‐treated mice (P = 0.004)." (PMID 29084756, 2017). "IDH1 and IDH2 mutations are also responsible for hypermethylation, decreased differentiation, and increased stemness of cancer cells as well as HIF-1α-mediated angiogenesis and growth of tumour." (PMID 28373964, 2017). "It has been reported that hypoxia also augments macrophage-mediated T-cell suppression, as targeted deletion of HIF1-α in macrophages inhibited ArgI production and T-cell suppression, resulting in tumor growth inhibition." (PMID 28197019, 2017). "In this study, with IHC assay, we found out that HIF-1α and Ki-67 protein were elevated in tumor tissue, both from HCC patients and mice model." (PMID 29238266, 2017). "Our results indicate that BA/CDM combination suppresses tumor growth through ROS formation and HIF1α pathway suppression." (PMID 29212263, 2017). "SIRT3 acts as a tumor suppressor, at least in part via its ability to suppress reactive oxygen species (ROS) and regulate hypoxia inducible factor-1-alpha (HIF-1α)." (PMID 28197299, 2017). "Elevated HIF-1α and LOXL2 expression was associated with an increase in tumor grade and VM (p < 0.05)." (PMID 28449718, 2017). "Here in the study, expression of HIF-1α increased significantly in periphery of necrotic tumor regions and tumor periphery one month after TACE and positive expression sustained two months later, which was in accordance with the pattern of alterations in MTA1." (PMID 28589145, 2017). "Inhibiting the expression of HIF-1α to promote tumor radiosensitivity has been demonstrated in various preclinical studies." (PMID 28410229, 2017). "This implies a potentially important interactive effect between tumor hypoxia and HIF-1α inhibition on radiation treatment response." (PMID 28619042, 2017).
tumor (continued). "We observed clear 8-nitroguanine formation in the tumor cells and inflammatory cells in patients with malignant fibrous histiocytoma (MFH), while HIF-1α expression was observed in the tumor cells." (PMID 28825631, 2017). "Our results provide new evidence that knockdown of NRF2 can suppress tumor angiogenesis by decreasing transcriptional activity of HIF-1α and inhibiting the expression of PDGF and VEGF gene." (PMID 29268703, 2017). "In order to address the impact of HIF-1α on NK cell-dependent tumour growth control in vivo, we conducted experiments with subcutaneous isografts of V-abl lymphomas that are subject to NK cell-mediated killing." (PMID 29150606, 2017). "And then we implanted Gl261 HIF1α-ShRNA cells into mice brain and found the tumor size in this group was much smaller than control with the same tumor cells seeded." (PMID 28427209, 2017). "Inhibition of Hif1-α synthesis abrogates growth stimulatory effects of exercise in one of the three tumor models." (PMID 29254140, 2017). "Immunohistochemical analysis demonstrated that YC-1 + GI reduced HIF-1α expression and pimonidazole accumulation in tumours." (PMID 28978999, 2017). "Expression of HIF-1α in tumor tissues was inhibited remarkably after the administration of TFAE, suggesting that the regulatory effect of TFAE on apoptosis of tumor cells is associated with the downregulated level of HIF-1α." (PMID 29348766, 2017). "This revealed increased tumour hypoxia despite increased angiogenic activity HIF-1α KO mice that preceeds differences in tumour growth kinetics." (PMID 29150606, 2017). "mTORC1/2 activation and HIF-1α/2α expression were also remarkably downregulated in WYE-687-treated tumor tissues." (PMID 28257457, 2017). "Hypoxia inducible factor 1alpha (HIF-1α) plays a critical role in the response of tumors to hypoxia, and contributes to tumor aggression, invasion and resistance to radiotherapy and chemotherapy." (PMID 28978182, 2017). "Western-blot and RT-PCR were used and we found HIF1α expression of the tumor sample raised in hypoxia was about three to four times higher than control including normal brain tissues and tumor sample obtained from normoxia (21% O2) raised mice." (PMID 28427209, 2017). "In tumor-bearing model mice, HIF-1α-siRNA-SWCNT complexes also effectively impeded the tumor HIF-1α activity." (PMID 30970690, 2017). "HIF-1α is recognized as an important regulatory protein in the transcription of a variety of tumor related factors including VEGF-A and VEGFR2." (PMID 27999191, 2017). "According to the results, decreased the expression of ATM is linked with angiogenesis and HIF-1α expression in HNSCC cells, suggestion that specific inhibitor regulating ATM pathway would be beneficial for suppressing tumor angiogenesis." (PMID 28881600, 2017). "All tumor groups except 468-shCDH1-B displayed positive HIF-1α staining, consistent with HPX occurring within these tumors." (PMID 28750639, 2017). "Echoing with in vitro finding that GATA3 augmented cell invasiveness under hypoxia, immunohistochemistry of tumour xenografts showed that expression of HIF-1α was significantly increased in GATA3 overexpressing tumours compared with control tumours." (PMID 28263977, 2017). "ZIR700-mediated PDT increased the number of HIF1α-expressing cells in tumor grafts over time, indicating the intensification of hypoxia in tumor grafts." (PMID 29182023, 2017). "HIF-1α, a key mediator of hypoxia response, has been revealed to play critical roles in tumor metabolism." (PMID 28886081, 2017). "Higher tumor levels of hypoxia as measured by hypoxia-inducible factor 1α (HIF-1α) expression have been shown to correlate with poor prognosis in patients with PDAC." (PMID 28316954, 2017). "MGC803 and SGC7901 cells were cultured to form tumor spheres, which were exposed to hypoxic or normoxic conditions for 48 h, followed by qRT-PCR and western blotting for HIF-1α and Snail." (PMID 28076840, 2017).
tumor (continued). "It should also be considered that the mechanisms and factors involved in HIF-1α regulation are cell-type specific, while the data shown in our bioinformatics analysis are representative of the whole tumor tissue." (PMID 29212519, 2017). "Hypoxia is an initial inducer of malignant transformation and tumor metastasis, and HIF-1α plays an important role in regulating tumor angiogenesis." (PMID 29282026, 2017). "That means in the tumor region, which had a higher HIF-1α level, EPO also expressed higher and cells grew faster." (PMID 29238266, 2017). "For instance, HIF-1α is responsible for the polarization towards the M2-like phenotype of tumor-associated macrophages (TAM), promoting therefore tumor growth." (PMID 28892492, 2017). "A second target of Hif1-α signaling, the cytokine Leptin, was dramatically increased in the dysplastic retina transcriptome (∼500-fold) and remained elevated in tumor tissue." (PMID 28192065, 2017). "The ability of Che-1 to regulate HIF1-α stabilization, provides a novel metabolic target for tumor treatment." (PMID 28214471, 2017). "Specific HIF-1α deletion in T cells resulted in defective effector differentiation and accelerated tumor growth, once again demonstrating that the contribution of HIF to cancer progression is dependent on the cellular context." (PMID 29136509, 2017). "Stabilisation of the HIF-1α subunit occurs, e.g., in the case of a deletion or inactivating mutation in the gene for the VHL protein, which determines the development of tumours, such as human glioblastoma or sporadic renal cell carcinoma." (PMID 27326424, 2017). "In our metformin dose response pilot study using 4–28 human patient-derived tumor fragments, HIF1α levels were reduced even at the lowest metformin concentration (50 mg/kg)." (PMID 29211738, 2017). "Hypoxia causes a rapid, dramatic, and selective upregulation of PD-L1 in splenic myeloid-derived suppressor cells (MDSCs), macrophages, DCs, and tumor cells in tumor-bearing mice through HIF-1α." (PMID 27974689, 2017). "The observed effect of metformin on HIF1α is important, as many tumor microenvironments are hypoxic, providing the stimulus for HIF1α protein stabilization, which is associated with increased angiogenesis and cell survival." (PMID 29211738, 2017). "Accordingly, attenuating HIF-1α-induced tumor angiogenesis is a potential strategy for cancer treatment." (PMID 28710377, 2017). "Surprisingly, HIF-1α KO mice showed a reduction of tumour volumes of more than 80% compared to tumours from WT littermates at endpoint (day 18)." (PMID 29150606, 2017). "Combination of AB/CDM exerts additive inhibition effect on AML tumor growth through HIF1α pathway suppression and ROS over-generation." (PMID 29212263, 2017). "Our study provides preclinical evidence that Pter/SAHA combination treatment inhibits MTA1/HIF‐1α tumor‐promoting signaling in PCa." (PMID 29024573, 2017). "Next, we sought to determine the impact of the HIF-1α-sVEGFR1-axis in NK cells on angiogenesis and growth of tumours with different levels of VEGF bioavilability." (PMID 29150606, 2017). "HIF-1α is one of hypoxic-related genes helps tumor cells adapting to the low nutrient and oxygen microenviroment." (PMID 29137372, 2017). "Comparison of the immunohistochemical data and clinicopathological variables revealed that the only statistically significant association was between tumor size and CAIX or HIF-1α overexpression." (PMID 28099149, 2017). "By promoting HIF1-α expression, a hypoxic tumor microenvironment can induce EMT, thus enhancing the tumor’s invasive and migratory abilities." (PMID 28449718, 2017). "It is well reported that HIF-1α plays a major role in tumor proliferation, angiogenesis, migration, and invasion in tumors." (PMID 29050246, 2017). "Since hypoxia destroys both tumor cells and normal cells, the expression of HIF-1α must be maintained in normal tissues." (PMID 28053598, 2017).
tumor (continued). "In conclusion, Compound 12, a benzopyranyl 1,2,3-triazole, demonstrates strong inhibitory activity against HIF-1α stability and transactivation, thereby showing both anti-angiogenic and anti-tumor activity." (PMID 27999195, 2017). "HIF-1α is the transcription factor in charge of the cellular response to hypoxia, including generated by a growing malignant tumor environment that consists mainly in angiogenesis and apoptosis." (PMID 28278159, 2017). "HIF-1α overexpression is also mediated by aberrant activation of oncogenic signaling providing a mechanism for adaptation to hypoxia by tumor cells, in addition to hypoxia-mediated mechanisms." (PMID 28841148, 2017). "When HIF-1α-deficient OT-I cells were transferred into B16-OVA tumor-bearing WT recipient mice, they were completely deficient in their ability to control tumor growth, leading to decreased survival." (PMID 29136509, 2017). "Secondly, this HIF-1α species is prevented from degradation under normal oxygen levels that are optimal for tumor cell growth." (PMID 28380438, 2017). "Specifically, they propose that tumor cells induce hypoxia-inducible factor 1α (HIF-1α) and nuclear factor κB (NF-κB) in CAFs and drive autophagy in CAFs, leading to nutrient release to support tumor cell metabolism." (PMID 28467800, 2017). "We find that 200μM succinate already can stimulate VEGF production and promote tumor angiogenesis beyond HIF-1α." (PMID 28061458, 2017). "Immunohistochemistry findings indicated that YC-1 + GI inhibited HIF-1α expression in xenograft tumours, and this combination coincidently decreased pimonidazole expression." (PMID 28978999, 2017). "Our results presented here showed that simultaneous inhibition of GLUT-1 and HIF-1α promoted tumor cell apoptosis more effectively than did inhibition of GLUT-1 or HIF-1α alone." (PMID 28410229, 2017). "Most cancer cells induce the expression of HIF-1α for their survival in a hypoxic tumor microenvironment." (PMID 28690762, 2017). "All treatments caused a significant inhibition of tumor expansion compared to the control, but the combination treatment with DDP and si-HIF-1α had the greatest antitumor effect." (PMID 28790395, 2017). "HIF-1α hydroxylation allows recognition by the von Hippel-Lindau (VHL) tumor suppressor, which targets HIF-1α to the proteasome for degradation." (PMID 28320353, 2017). "The activated tumor glycolytic flux involving HIF-1α implies upregulation and increased activity of several glycolytic protein including key glycolytic enzymes (HK2, PFK-L, PKM2, and LDH-A) and GLUT (GLUT1 and GLUT3)." (PMID 28348562, 2017). "Our results, showed that the expression of HIF-1α correlated with TWIST1 expression in tumor site of the Group 1 patients." (PMID 29152120, 2017). "SL4 therefore inhibited tumor invasion and angiogenesis by suppressing HIF-1α activity and induced apoptosis by promoting reactive oxygen species release." (PMID 29271940, 2017). "The effect of AZD5363 on HIF‐1α was investigated by immunohistochemistry (IHC) in fixed tumour tissue." (PMID 29084756, 2017). "In this context, it should be noted that contrary to tumor cells, low glucose content in non-tumor cell lines has been shown to increase the stability of HIF1α." (PMID 27682873, 2017). "Microbead-induced increases in tumour formation (i.e. those observed when beads were given after LLC injection) were accompanied by concomitant increases in both pulmonary HIF1α and pulmonary HIF2α expression." (PMID 28302670, 2017). "The results demonstrated that the treatment of tumor-bearing mice with attenuated Salmonella carrying the HIF-1α siRNA plasmid greatly enhanced the antitumor effects of low-dose DDP." (PMID 28790395, 2017). "All of these findings suggest a novel mechanism whereby downregulation of SIRT3 in H. pylori CagA+ infected gastric cells induces ROS, HIF-1α activity, and tumor growth." (PMID 29108235, 2017).
tumor (continued). "For example, the AMPK-less tumor cells showed increased glucose consumption, increased lactate production and upregulation of transcription factor HIF-1α and its glycolytic downstream targets (LDH-A, PDK1, and ALDA)." (PMID 28443281, 2017). "We further investigated the correlation between GATA3 and HIF-1α expression in the 151 HNSCC tumours by immunohistochemistry, and the results confirmed a significantly positive correlation (Pearson’s correlation coefficient=0.54, P<0.001)." (PMID 28263977, 2017). "HIF-1α is a major regulator in helping cells survive hypoxia and has been confirmed to promote metastasis by regulating tumour cell migration and invasion." (PMID 28507454, 2017). "The roles of hypoxia-inducible factor-2α (hif-2α) are different to those of hif-1α, although both are critical for tumor cells to adapt to the hypoxic microenvironment." (PMID 28705232, 2017). "This work reveals a new role of STK33 during tumor progression, namely the participation to the regulation of HIF-1α and its target gene VEGF-A in hypoxic cancer cells." (PMID 29100402, 2017). "When tumor cells are exposed to hypoxic conditions, HIF-1α up-regulates several genes promoting the growth and survival of tumor cells." (PMID 29179449, 2017). "OXY111A, a synthetic allosteric effector of hemoglobin to promote normoxia in hypoxic tumors, has been shown to prevent HIF1α stabilization as well as VEGF production in tumor masses." (PMID 28493839, 2017). "The number of HIF-1α positive cells as well as the intensity of staining can vary in the tumor zone." (PMID 29312568, 2017). "In the hypoxic tumor microenvironment, HIF-1α protein escapes degradation and translocates into the nucleus, where it initiates a gene expression program that leads to a switch from oxidative phosphorylation to glycolysis." (PMID 28471448, 2017). "The number metastic nodules in the lungs of LLC-bearing animals was similar across genotypes, despite a pronounced reduction in the size of primary tumours from HIF-1α KO mice." (PMID 29150606, 2017). "Taken together, metformin ameliorated tumor hypoxia and restrained HIF-1α-induced expressions of AAFs through elevating tumor blood perfusion, thus suppressing the excessive tumor angiogenesis." (PMID 29088755, 2017). "MiR-494 is a tumor-derived pro-angiogenic stimulus upregulated via HIF-1α-mediated transcriptional activation." (PMID 29383199, 2017). "Co-expression of TrkB and HIF 1α were visualized by immunofluorescence staining, and immunohistochemistry revealed that VEGFs were more highly expressed in the tumor margin than in the tumor center, where TrkB and HIF-1α were also overexpressed." (PMID 28423707, 2017). "Vessel function in Mac-NG2ko tumors was further compromised by a decrease in vessel patency and by an increase in vessel leakiness, resulting in a large increase in tumor hypoxia and a 2-fold rise in HIF-1α expression." (PMID 28788063, 2017). "Cobalt chloride (CoCl2), a well-known hypoxia-mimicking agent in vitro, which blocks HIF-1α degradation and thus causes HIF-1α accumulation in cells, therefore leading to an intracellular hypoxia-like microenvironment and enhancing tumor malignancy." (PMID 29026004, 2017). "Hypoxia inducible factor 1α (HIF1α) and glucose metabolism can change the tumor microenvironment, and HIF1α plays a critical role in regulating tumor angiogenesis in response to hypoxia." (PMID 28903449, 2017). "It is regulated by HIF-1α, overexpressed in the hypoxic tumours and is involved in cell proliferation." (PMID 28756482, 2017). "HIF-1α regulates multiple genes and signaling pathways including cancer cell survival, tumor neovascularization, and metabolism, which directly and indirectly impact antitumor immunity." (PMID 28348554, 2017). "HAF switches cells from HIF-1α to HIF-2α via this subset of HIF-2α-dependent genes that drive tumor progression, and result in poor patient prognosis." (PMID 28572533, 2017).